MS4A13 (membrane spanning 4-domains A13)
Description:
May be involved in signal transduction as a component of a multimeric receptor complex.
Tractability: Antibody: UniProt predicts a signal peptide or a membrane-spanning region; its Gene Ontology location is reachable by antibodies, with medium confidence.
Gene: Protein-coding gene on chromosome 11 (60,515,392 to 60,542,721, forward strand). Ensembl gene ENSG00000204979.
Subcellular location: Membrane
Gene Ontology:
Molecular function: protein binding
Biological process: cell surface receptor signaling pathway
Cellular component: plasma membrane; membrane
Genetic constraint (gnomAD): Loss-of-function variants: 5 observed, 6.62 expected, observed/expected ratio (o/e) 0.76, 90% interval 0.39 to 1.55. That is too few expected variants to judge how well the gene tolerates losing a copy. Missense variants: 47 observed, 44.07 expected, observed/expected ratio (o/e) 1.07, 90% interval 0.84 to 1.36. Synonymous variants: 18 observed, 13.28 expected, observed/expected ratio (o/e) 1.36, 90% interval 0.93 to 1.86.
Homologues: Orthologues: chimpanzee MS4A13 (97% identical), macaque MS4A13 (80% identical), dog MS4A13 (71% identical), rabbit MS4A13 (66% identical), mouse Ms4a13 (63% identical), rat Ms4a13 (61% identical), guinea pig MS4A13 (59% identical), pig MS4A13 (59% identical), zebrafish ms4a17a.1 (24% identical), zebrafish tmem176l.3a (24% identical), zebrafish si:ch73-56d11.3 (24% identical), zebrafish si:dkey-77f5.10 (24% identical), and 21 more. Paralogues in human: MS4A5 (23% identical), MS4A18 (22% identical), MS4A4A (22% identical), MS4A8 (22% identical), MS4A12 (22% identical), MS4A2 (21% identical), MS4A7 (20% identical), MS4A6A (20% identical), MS4A15 (18% identical), MS4A3 (18% identical), MS4A10 (18% identical), MS4A1 (17% identical), and 4 more.
Diseases named in the same sentence as MS4A13 in open-access papers:
MS4A13 is named in the same sentence as 1 disease in open-access papers, as found by Europe PMC text mining. Sharing a sentence is not in itself a finding about the gene and the disease.
MS4A13 shares sentences with these, for which no sentence is quoted: glioma (1 paper).